TNF (tumor necrosis factor)
Diseases named in the same sentence as TNF in open-access papers (continued):
Sharing a sentence is not in itself a finding about the gene and the disease.
tumor (continued). "In vitro studies have shown that butyrate also exhibits antitumor effects, including the reduction of the secretion of tumor necrosis factor (TNF) in intestinal epithelial cells, and induction of the differentiation and apoptosis of tumor cells, thereby inhibiting tumor growth." (PMID 33641084, 2021). "These immune responses include a host of antitumor immune cells being recruited and producing an array of cytokines, such as TNF‐α and IL‐12, which are not conducive to established tumor growth." (PMID 34633664, 2021). "In addition, the inhibition of FAK, the critical kinase mediating both TNFα and IL1β signaling, effectively ameliorated endothelial dysfunction induced by CAR-T/tumor cells/myeloid cells." (PMID 34093519, 2021). "Strikingly, siRNA-mediated silencing of SIGLEC15 in SN increased the secretion of anti-tumor cytokines, including IL2, IFN-γ, and TNF-α, suggesting that inhibiting SIGLEC15 expression in SNs could restore T cell function." (PMID 34722496, 2021). "Although dose‐related increase of several proinflammatory cytokines (such as IL‐1β, TNF‐α, IL‐6, and IL‐12) was observed, no patients experienced objective tumor regression." (PMID 33854892, 2021). "The serum levels of IFN-γ and TNF-α increased significantly after IPLD treatment and returned to the normal levels after healing, but increased greatly again upon the second inoculation and enabled mice to reject the rechallenged tumours." (PMID 33893275, 2021). "In accordance with scRNA-seq data, the Oxali + anti–PD-L1 combo increased the percentage and/or total numbers of tumor-infiltrating CD8+ and CD4+ T cells, CD107+IFNγ+ CTLs, IFNγ+ CD8+, and TNF+IFNγ+ CD8+ T cells, CD8+CD44+ Teff cells, and CD8+CD44+PD1+TIM-3+ T cells analyzed by flow cytometry." (PMID 33602823, 2021). "Regardless of the upregulation of PD-L1 attributed to REG, the immunosuppressive TME of CT26-Luc tumor was distinctly relieved of the effects of BMS202, characterized by the increased infiltration of CD8+ T cell in CT26-Luc tumor and enhanced secretion of antitumour cytokines (IFN-γ and TNF-α)." (PMID 33935796, 2021). "TAMs modulate the CCA microenvironment by secreting TNFα, TGFβ (tumor growth factor-β), IL6, IL10, and VEGF-A (vascular endothelial growth factor-A), which support epithelial-to-mesenchymal transition (EMT), tumor growth, and metastasis." (PMID 33579265, 2021). "To determine the effector capacity of tumor-infiltrating T cells (TILs) from NC410-treated mice, we re-stimulated TILs from digested tumors with anti-CD3 plus anti-CD28 for 5 hr and performed intracellular staining to examine IFN-γ and TNF-α production." (PMID 34121658, 2021). "However, obese CXCR2 cKO mice had a greater OC-induced ascites accumulation, showing reduced ascitic floating tumor cells and tumor-attached Mo/Mφ with lower triglyceride, free fatty acid, CCL2, and TNF levels compared to obese WT mice." (PMID 34638514, 2021). "However, it has been investigated that the interaction between TNF-α and TGF-β is also two-sided during tumor formation." (PMID 35069596, 2021). "The cytolytic activity of TCR-TMART-1 was inhibited by increasing the percentage of tumor cells expressing PD-L1, affecting the secretion of Granzymes and pro-inflammatory cytokines in Tnull and TCR-TMART-1, including TNFα, IFNγ, and IL2." (PMID 33754038, 2021). "Other cytokines (CCL2, IFNγ, IL-12, IL-10, TNFα, IL-4, and IL-1β) evaluated were not significantly changed, suggesting that additional unidentified tumor-derived soluble factors promote alternative activation in BMDMs." (PMID 35008514, 2021). "For example, Salmonella LPS could be involved in tumor-specific CD8+ T cell responses and the elevation of TNF-α." (PMID 34138211, 2021). "Of note, inflammatory cytokines such as TNFα, IL-6, and IL-8 and platelet agonists such as thrombin and ADP in the tumor microenvironment could promote platelet autophagy and then activate platelets, leading to thrombosis and cancer metastasis." (PMID 34722319, 2021).
tumor (continued). "Although NAX014 did not modulate the presence of tumor-infiltrating lymphocytes, the level of circulating TNF-α and VEGF was found to be reduced in NAX014-treated mice." (PMID 33800754, 2021). "In addition, BJJP treatment also promoted the effector function of CD8+T cells by significant increasing the expression of TNF-α and IFN-γ in tumor-infiltrating CD8+ T cells." (PMID 34899325, 2021). "In contrast, mast cells could secrete tumor necrosis factor α (TNF-α) and directly mediate tumor cell cytotoxicity, thus playing an antitumorigenic role." (PMID 34277151, 2021). "Other factors such as TGF-β, TNF, WNT7B, and thymidine phosphorylase promote tumor progression by recruiting and activating endothelial or other cells (such as fibroblasts) that further support angiogenesis in the tumor microenvironment." (PMID 34178692, 2021). "This promiscuous interaction, in some cases, can block the activation of the apoptotic pathway, as in the case of TNF-α that induces apoptosis via TNF-R1 and TNF-R2 and can lead to tumor progression, and TRAIL also binds to decoy receptors (DcR1 and DcR2) that do not induce apoptosis." (PMID 33801589, 2021). "Moreover, IL-1 beta-induced expression of TNF-alpha, IL-6, IL-8, IL-17, COX-2, and PGE2, pro-inflammatory mediators, and pro-tumor factors supporting tumor growth cells." (PMID 35008550, 2021). "The authors reassuringly reported no change in tumour response in patients treated with either DMARDs or TNF inhibitors." (PMID 33423684, 2021). "TNF-α, which is found in the TME, is secreted by macrophages, lymphocytes and natural killer (NK) cells and mediates the production of proinflammatory factors that elicit tumor growth and recently emerged as a promising cancer therapy target." (PMID 34830910, 2021). "M1-like macrophages were described as highly phagocytic and highly inflammatory and could facilitate anti-tumor immune response in the TME by secreting nitric oxide, reactive oxygen species (ROS), and inflammatory cytokines, including TNF-α, IL-1 and IL-6." (PMID 34512367, 2021). "In addition, TAMs play an important role in tumor neovascularization by secreting proangiogenic factors, such as VEGF, TNF, IL-1β, IL-8, PDGF, FGF, and others." (PMID 33916915, 2021). "These included IL-12p70, pro-inflammatory IL-1β, and TNF, as well as MIP-3α (CCL20) and MIP-3β (CCL19), which are chemotactic for lymphocytes and DCs, and IFN-α, which is known to activate antigen presentation for T cell-mediated tumor cell recognition." (PMID 34912334, 2021). "Interestingly, the current study revealed that TNF α - activated caspase-8 switched apoptosis to pyroptosis in the presence of hypoxia-activated GSDMC and nPD-L1, leading to tumor necrosis in hypoxic regions." (PMID 35047554, 2021). "IL-6 is the major cytokine that stimulates proliferation of tumor cells, and it inhibits apoptosis via activation of the STAT3 signaling pathway 18 TNF-α could activate NF-κB and AKT signaling cascades and stimulate tumor progression." (PMID 33391471, 2021). "Besides, TNF-α, as the prototype of the TNF superfamily cytokines, has been validated to enhance the differentiation of Th9 cell and exert anti-tumor immunity effect via TNFR2-dependent pathways." (PMID 33558586, 2021). "In hypoxia status, tumor cells inhibited immune cells’ antitumor ability by interacting with inhibitory receptors in immune cells like PDCD1, TIGIT, and LILRB or weakening the immune-stimulation ligand–receptor interactions such as CCL, TNF, and FASLG." (PMID 34956900, 2021). "M1 macrophages are induced by Th1 cytokines such as interferon γ (IFNγ) and tumor necrosis factor α (TNF-α) or by lipopolysaccharide (LPS) and typically attack microorganisms and tumor cells, and express inducible nitric oxide synthase (iNOS) and most of the TLRs." (PMID 34946714, 2021).
tumor (continued). "Because TNF-α induces diverse effects in TME, both oncogenic and tumor-suppressive effects, further studies are warranted to fully understand and selectively induce the anti-tumor effect to improve treatment efficacy in patients with TNF-α sensitive cancers." (PMID 33986746, 2021). "It is important to highlight that, in the tumor microenvironment, CXCL9-10-11 chemokines are secreted mainly by endothelial cells, fibroblasts, and cancer cells in response to IFN-γ, which are synergistically increased by TNF." (PMID 34335758, 2021). "In summary, based on the bifacial nature of TNF-α and TGF-β in the body microenvironment, this article describes the interaction between the two in the process of tumor formation from five aspects: proliferation, apoptosis, inflammation, EMT and genomic instability." (PMID 35069596, 2021). "Increased inflammatory cytokines such as NF-KB, TNF-α, IL10, IL8, IL6, and increased levels of E. cadherin on epithelial cells activates B-catenin signaling, increases NF-κB, C-myc expression and proliferates tumor cells." (PMID 33823861, 2021). "Our current findings are suggestive of a potentially critical role for the TNFα/TNFR1 signaling pathway in the context of carcinogenesis and malignant progression through the inhibition of tumor invasion and modulation of the inflammatory response to malignant processes." (PMID 34650923, 2021). "In addition, NK cells can also secrete cytokines, such as interferon (IFN)-γ and tumor necrosis factor (TNF)-α, to inhibit tumor cell proliferation, tumor angiogenesis, and multistage canceration." (PMID 34401208, 2021). "In PaCa, tumor-derived exosomal miRNA-203 was reported to downregulate TLR4 and downstream tumor necrosis factor α (TNF-α) and IL-12 in DCs, which may help PaCa cells achieve immune escape." (PMID 34243775, 2021). "Finally, combinatorial treatment with tamoxifen, TNFα and short–hairpin (sh)-NCOR1 resulted in enhanced suppression of tumor growth in MCF7 xenograft mice compared to single tamoxifen treatment." (PMID 34073371, 2021). "The broad non-specific effects of TNF-α infusion in patients initially led clinicians to abandon this signaling pathway as first-line therapy against neoplasms." (PMID 34712661, 2021). "Moreover, pro-inflammatory cytokines (IFN-γ, TNF-α) and chemokines (CCL3, CCL4, and CCL5) secreted by NK cells stimulate other lymphocyte populations in the tumor microenvironment or exert a direct anti-tumor effect." (PMID 34203935, 2021). "MT1H may function in regulating cellular response to zinc ions and negatively modulate tumor growth via the downregulation of the inflammatory pathway, Jak–STAT pathway, TNF pathway, and Wnt signaling pathway." (PMID 34676244, 2021). "One approach to mimic the inflammatory niche is to generate TNF-α-primed-hBMMSCs that secrete high levels of CCL5, which is involved in the CRC-related CCl5/CCR1/β-catenin/Slug signaling pathway that promotes tumor cell proliferation, EMT, migration, and invasion." (PMID 33849537, 2021). "In addition to T cells, the activation of eosinophils can also normalize tumor blood vessels, but the exact mechanism is unclear, which may be that the TAMs were polarized into an M1-like phenotype through eosinophil-derived IFNγ and TNF signaling, leading to a reduced low VEGF production." (PMID 34476218, 2021). "Notably, radiotherapy is also sufficient to increase local TNF and enhance tumor MHC-I expression, possibly with less systemic toxicity than systemic exogenous TNF." (PMID 34277419, 2021). "However, in CD105-negative CAFs, the STING1, NFκB, IL-6, TNF-α, JAK2, and LTBR signals observed high expression and remarkably performed tumor suppression." (PMID 35265630, 2021). "Given the innate ability of NK cells to lyse tumor cells and secrete potent anti-tumor cytokines, such as IFN-γ and TNF, prior to immunization, we hypothesized that NK cells of unique phenotype may infiltrate different cancers and confer anti-tumor immunity." (PMID 34539622, 2021).
tumor (continued). "In parallel to increased ATP release, tumor microenvironment conditions may increase CD39 and CD73 expression through various inflammatory mediators, such as TGF-β, IFNs, TNF, IL-1β, and prostaglandin E2." (PMID 33807260, 2021). "Iron nanoparticle injection has been shown to induce M1 polarization, triggering apoptosis of cancer cells via an autocrine feedback loop that maintains TNF-α and nitric oxide within the TME to continuously inhibit tumor growth, reduce cell migration, and inhibit pulmonary and hepatic metastasis." (PMID 33986740, 2021). "TNF-α and IFN-γ in tumor tissues were measured on the 14th day." (PMID 33792840, 2021). "Our data show that lymphotoxin alpha and not TNF derived from the tumor cells requires cIAP1 expression in the endothelium to induce tumor cell extravasation." (PMID 33546280, 2021). "(F–H) Multiplex analysis of inflammatory chemokines (TNFα, RANTES, and GrzmB) produced by fresh KPC tumor slices kept in culture for 18 hr (*** p-value<0.001, * p-value<0.05, one-way ANOVA, Krustal Walis, n = 8 slices per condition from two independent experiments)." (PMID 34106045, 2021). "Interestingly, TAMs are mobilized to the peripheral blood and then recruited in the PMNs by many tumor-secreted cytokines and growth factors (e.g., CCL2, CSF-1, VEGF, PLGF, TNF-α, TGF-β), tissue inhibitor of metallopeptidase (TIMP)-1, and exosomes." (PMID 33916915, 2021). "In many types of cancers, tumor cells secrete the chemokine CXCL12 to induce the infiltration of a large number of immature pDCs, and the cytokines of VEGF, TNF-α, TGF-β and IL-10 secreted in tumor microenvironment inhibit the maturation and activation of pDCs, then make it unable to produce IFN-α." (PMID 34737750, 2021). "Although IL-6 and TNF-α concentrations were not significantly different between our groups, their involvement in tumor growth should not be overlooked." (PMID 34439874, 2021). "Drug-containing hydrogels injected into the tumor site can gradually release DOX and DPPA-1, which play a synergistic role in enhancing the infiltration of cytotoxic CD8+ T cells in tumors and inducing the secretion of TNF-α and IFN-γ at the highest level." (PMID 34842684, 2021). "Other than exerting a relevant cytotoxic activity, both generations of CAR-transduced T cells also produced high and comparable levels of IFN-γ, IL-2, and TNF-α in response to PSMA-expressing tumor targets, but not against PSMA negative control cells." (PMID 34660275, 2021). "More straightforward was the negative role described for TNFα secretion by TAMs, as this promoted cell glycolysis, tumor hypoxia, and decreased PD-L1 expression." (PMID 34445397, 2021). "Thus, we prepared gold nanoparticles (Nps) bearing TNF and/or IL12 and c(CGisoDGRG) (iso1), a head-to-tail cyclic peptide that recognizes αvβ3 integrin overexpressed in the tumor vasculature." (PMID 33952242, 2021). "Moreover, miR-125b-5p silencing has increased cytotoxic effects of γδ T cells against tumor cells through enhancing the production of IFN-γ and TNF-α." (PMID 34804042, 2021). "Neither the epithelial cell-derived HEK293-Exo nor tumor-derived SKOV3-Exo induced an immune response in PBMCs evaluated by TNF-α (Tumor necrosis factor alpha) and INF- α (Interferon alpha) production." (PMID 34199901, 2021). "Interestingly, flavonoid wogonoside (a glucuronide of wogonin), a main in vivo metabolite of wogonin, inhibited the tumor invasion and migration in TNF-α-induced MDA-MB-231, MDA-MB-435, and BT-474 cells through the decreased level of TNF-α." (PMID 32521759, 2020). "LIF was actively secreted by C26 tumor cells, whereas TNF-α and IL-6 were not, and incubation of C2C12 myotubes with LIF was sufficient to induce atrophy." (PMID 33329046, 2020). "Notably, EV isolated from MSC of HL patients and HL tumor cell lines treated with the specific ADAM10 inhibitors retain the ability to inhibit shedding of the ADAM10 substrates MICA, tumor necrosis factor (TNF)α and CD30 in recipient cells." (PMID 32668783, 2020).
tumor (continued). "TNF-α produced by tumor cells induced c-MET expression in neutrophils via activation of NF-kB, further illustrating how the prevailing cytokine milieu can ignite anti-tumor effector functions in neutrophils." (PMID 32117721, 2020). "In addition to TNFα, other cytokines (e.g., interleukin-1, IL1) stimulate an inflammatory program and coordinate tumor-infiltrating leukocytes (TILs) in tumor milieu via activation of pro-inflammatory chemokines." (PMID 32244522, 2020). "In solid tumors the role of NK cells may appear less relevant, however their activation may support a first line of tumor control by cytolytic activity, IFN-γ and TNF-a production, and by stimulating Th1 response through DCs editing." (PMID 32218226, 2020). "In one study, MDSCs that accumulated around the germinal center co-localized with B cells in the spleen of tumor-bearing mice, and cell-to-cell interaction through TNFR2 on MDSCs and membranous TNF on B cells promoted the proliferation and differentiation of B cells into IgA-producing plasma cells." (PMID 32793192, 2020). "TNF is a cytokine that directly kills tumor cells and has no obvious toxicity to normal cells, and it is one of the most potent biologically active factors." (PMID 32149121, 2020). "In a cooperative manner with TNF-α, LTB4 may influence the growth, survival, invasion, and metastasis of tumor cells." (PMID 32973519, 2020). "One of the key immuno-modulatory effects of SMs is their ability to potentiate TNF-mediated bystander killing of tumour cells." (PMID 31947615, 2020). "Tumor growth, blood lymphocyte levels, cell cycle progression, apoptosis, apoptotic regulator expression, TNF-α expression, changes in mitochondrial membrane potential (MMP), PCNA, and CD4+ and CD8+ T cells in tumor cells were quantitatively evaluated by flow cytometry or RT-PCR." (PMID 32345289, 2020). "Besides, cytokines such as TNF-α, IL-1α/β, or IL-6 can trigger STAT3 signaling transduction and NF-κ B transcription, promoting tumor cell proliferation and survival as well as immune response." (PMID 32410986, 2020). "A study of tumor-bearing mice found that APS could enhance the immune function by increasing the levels of cytokines, such as IL2, IL6, IL12, and TNF-α." (PMID 32265719, 2020). "Mechanistically, tumor lysates stimulated SOCS3 knockout macrophages in vitro, their STAT3 phosphorylation is enhanced and TNF-α and IL-6 are reduced, and higher levels of MCP2/CCL8 via STAT3 are produced to combat tumor metastasis in contrast to normal macrophages." (PMID 33224886, 2020). "Additionally, it was found that the lysate of L. acidophilus promoted the anti-tumor effects of CTLA-4 by reducing the quantity of Treg as well as M2 cells, while increasing the levels of T cells and IFN-γ, Granzyme B, and TNF-α." (PMID 33318319, 2020). "Expression of the tumor-promoting inflammatory factor IL-6, immunosuppressive factor PD1, and PD-L1 increased, whereas expression of the immune factor TNF-α and body rhythm-related factors Per1 and Per2 decreased in the night-shift group, and the difference was statistically significant." (PMID 33083827, 2020). "The cells exhibiting an active cell cycle progression were reduced in tumor tissues of AIMP1-treated mice, and the blood levels of TNF-α and IL-1β were increased, indicating that AIMP1 might play an anti-tumor role by inducing tumor inhibiting cytokines." (PMID 32709848, 2020). "Activated CD8+ Teff are dominant antitumor cells that secrete granzymes, perforin, and pro-inflammatory cytokines, such as tumor necrosis factor (TNF) and interferon (IFN)-γ, whereas CD4+ T cells can either inhibit or promote tumor cell activity via the specific activities listed here." (PMID 35047983, 2020).